REL (REL proto-oncogene, NF-kB subunit)
Diseases named in the same sentence as REL in open-access papers (continued):
Sharing a sentence is not in itself a finding about the gene and the disease.
tumor (90 papers, 2002 to 2026). "Several members of the canonical NF-κB pathway were in the top list, including RELA, NFKB1, CHUK, IKBKB, IKBKG, and REL, indicating that the canonical NF-κB pathway was closely associated with immune-related DEGs in tumour serum-cultured DCs." (PMID 28350008, 2017). "The signature of ESR1-positive tumours was mainly linked to cell proliferation and regulated by ER, whereas the signature of ESR1-negative tumours was mainly linked to the immune response and possibly regulated by transcription factors of the REL/NFκB family." (PMID 19826428, 2009). "Crucially, we have delineated the intricate crosstalk between tumor metabolism and immune regulation, revealing that the REL transcription factor mediates glycolytic metabolite-induced IL-10 production in M2-TAMs." (PMID 40959090, 2025). "REL is a novel tumor oncogene in LUSC that contributes significantly to LUSC growth by facilitating cell proliferation and migration." (PMID 38495491, 2024). "This distinct subunit-specificity extends our discussion on RELA and/or c-REL being present in solid cancers by showing the subunit-specificity depending on the GBM tumor type." (PMID 36361720, 2022). "On a mechanistic level, we found TNFα-mediated activation of NF-κB RELA and/or c-REL depending on the tumor type." (PMID 36361720, 2022). "More specifically, chromosomal region 2p15‐16 (XPO1/REL) was gained in a higher proportion of tumor cells than the 2p24 region (MYCN) in eight of the 48 patients (17%)." (PMID 31066214, 2019). "Transcription factor (TF) activity prediction, using the DoRothEA resource, to identify potential regulons responsible for the signalling and phenotypes associated with HPS in HiFi tumours revealed a strong association with STAT1, STAT2, IFN (IRF1, IRF9) and NFκB (NFKB1, REL, RELA, RELB) TFs." (PMID 35477539, 2022). "Moreover, this drug inhibited c-REL function in T regulatory cells in an animal model of melanoma, thus delaying tumour growth." (PMID 36289712, 2022). "For example, c-REL may be a suitable target for GC tumours with strong NF-κB pathway activity, RELA for plasmablast-associated tumours, and RELB and/or NF-κB2 for the subset of DLBCL cases with nuclear translocation of these subunits." (PMID 36289712, 2022). "Next to NF-κB p65, the subunit c-REL was shown to possess a key role in tumor formation." (PMID 28767691, 2017). "At the molecular level, transcription factors such as STAT1, CEBPB, HIF1A, and REL, collectively drive MDSCs expansion, while chemokines like CCL3, CCL4, CCL8 and IL1B regulate their migration within the tumor microenvironment." (PMID 41252877, 2025). "Enrichment analysis showed that NF‐kB‐related factors (REL, RELA and NFKB1) were enriched in tumour Te‐EVs." (PMID 40326665, 2025). "Other major potential tumor growth factors, such as POU2F2, RUNX1, ERG, REL, and JUN, were also relatively increased in the low TEX-score group." (PMID 38629071, 2024). "TFs in XIST+ and S100A4+ tumor cells were similar, particularly RUNX3, REL, STAT4, and E2F1, which regulate the EMT process." (PMID 37430270, 2023). "Unlike GCB-DLBCL, however, both HL and MLBCL cases display nuclear translocation of c-REL, implicating a role for c-REL in the maintenance of HL and MLBCL tumor cells." (PMID 30380749, 2018). "Interestingly, the ESR1-negative tumours were substratified into two groups presenting slight differences in the magnitude of the expression of immune response transcripts and REL/NFκB transcription factors, which could be dependent on the type of BRCA1 germline mutation." (PMID 19826428, 2009). "In addition, miR-21 was reported to the regulate tumor suppressor and regulator of B-cell differentiation BTG2 and E3 ubiquitin ligase PELI1 which are known to regulate c-REL levels." (PMID 38539461, 2024). "In GC, NFKB1, NFKB2, REL, RELA, and RELB were significantly upregulated in tumor tissues." (PMID 35036435, 2022).
tumor (continued). "Likewise, elevated amounts of c-REL and NIK in the HRS cells due to gains and amplifications may enhance incoming signals from cell surface receptors activated by immune cells in the tumour microenvironment." (PMID 36289712, 2022). "It has therefore been proposed that enhanced c-REL activity provided by the amplification may have been required early in GCB-DLBCL pathogenesis, before becoming dispensable for tumor growth at later stages of tumor development." (PMID 30380749, 2018). "Indeed, earlier studies failed to obtain evidence of c-REL nuclear translocation in these tumours." (PMID 36289712, 2022).
cancer (64 papers, 2005 to 2025). A tumor composed of atypical neoplastic, often pleomorphic cells that invade other tissues. "The molecular identification of p65 subunit as a member of the reticuloendotheliosis (REL) family provided the first evidence that linked NF-κB to cancer, as v-REL is an oncoprotein of the REL retrovirus (REV-T)." (PMID 26318844, 2015). "The NF-κB subunit c-REL is also directly linked to cancer development and progression." (PMID 28767691, 2017). "To define the mechanism linking c-REL to EC proliferation, we initially investigated crosstalk with other NF-κB family members since these drive proliferation in cancer cells and other contexts." (PMID 39982773, 2025). "REL expression increases in a variety of B and T cell malignancies as well as in other cancer types." (PMID 32099610, 2019). "Next, by directly promoting cancer cell growth and proliferation, c-REL was very recently shown to possess an important role in cancer-targeting immune responses with highly promising implications for therapeutic approaches." (PMID 29673141, 2018). "Providing a linkage to cancer therapy, we discuss the recently described pivotal role of NF-κB c-REL in regulating cancer-targeting immune responses." (PMID 29673141, 2018). "The present study further extends these promising findings by showing a profound overexpression of c-REL in cancers located in human ovary, cervix and endometrium using database mining." (PMID 28767691, 2017). "NR4A2 is a family member of AR (NR3C4), which is known to be activated downstream of the MAPK pathway in cancer and directly interacts with NFκB (specifically the REL subunit), as correctly predicted for NR4A2." (PMID 27078000, 2016). "Many cancer cell types show high levels of constitutive activity of NF-κB transcription factors (p50, p52, RelA/p65, c-Rel/REL and RelB)." (PMID 25915462, 2015). "Translocation of NF‐kappa‐B/REL complexes to the nucleus enables these complexes to activate the transcription of mitogenic and anti‐apoptotic proteins, thus evading pro‐inflammatory signals, immune surveillance, and promoting cancer cell proliferation." (PMID 39513319, 2024). "By causing cell divisions, increasing cell motility, and stimulating the expression of genes including vascular endothelial growth factor (VEGF), hypoxia-inducible factors (HIF-1), vimentin (VIM), and REL proto-oncogene, NF-kB subunit (REL), Ang1-9 appears to have pro-cancer effects." (PMID 37891636, 2023). "With regards to the assessed overexpression of c-REL in human cancers, potential clinical implications of the c-REL knockout were assessed by determining cell survival upon exposure to the chemotherapeutic agents 5-Fluoro-2’-deoxyuridine (5-FUDR) and cisplatin." (PMID 28767691, 2017). "Thus, agents that modulate REL activity may have therapeutic benefits for chronic inflammatory diseases and human cancers." (PMID 32099610, 2019). "Additionally, a newly developed small molecule c-REL inhibitor showed anti-cancer cell properties in a xenograft model, although this inhibitor may not be c-REL-specific as it inhibited RELA function in another study." (PMID 30380749, 2018). "Expression of wildtype human c-REL in primary chicken spleen cell cultures was likewise shown to result in malignant transformation events, although respective mutations increasing the oncogenicity of the c-REL protein in the avian system were not observable in human cancers." (PMID 28767691, 2017). "Thus, much data indicate that REL may be a valuable target for certain types of anti-cancer and immunomodulatory therapies." (PMID 25915462, 2015). "To provide an overview on the occurrences of distinct NF-κB subunits in cancer subtypes, we assessed the overexpression of the NF-κB subunits RELA, RELB, and c-REL in human cancers by database mining, using COSMIC." (PMID 29673141, 2018).
cancer (continued). "This shows that genes containing conserved RELA, STATI, IRFI, NF-kappaB, PEND, HLF, REL, CEBPA, DI_2, and NFKB1 binding sites are indeed over-represented in cancer-related DEGs and this over-representation can be recuperated computationally." (PMID 29593668, 2018). "To assess the clinical implications of a c-REL knockout, we assessed levels of c-REL overexpression in human cancers by database mining using COSMIC." (PMID 28767691, 2017). "As shown, the expression of NFKB1, NFKB2, REL, RELA, and RELB varied in different cancer types." (PMID 35036435, 2022). "It included a number of genes with obvious cancer relevance including CD44, catenin b1 (CTNNB1), vimentin (VIM), cathepsins B and S (CTSB, CTSS), MMP9, XIAP, JunD, numerous proto-oncogenes (REL, YES, SET, FGR, CRK), and HSP90AA1 (which is a chaperone which stabilizes MIF as a client)." (PMID 28957348, 2017). "Therefore, the STAT/gp130/OSMR/JAK feedforward loop and NF-κB (REL, NFKB1) may operate combinatorially in cancer." (PMID 32102440, 2020).
infection (26 papers, 2009 to 2025). The state of being infected such as from the introduction of a foreign agent such as serum, vaccine, antigenic substance or organism. "In a large ICU population, we report a significant clinical association between a variation in the human REL gene and severity and mortality of septic shock, suggesting for the first time a new insight into the role of cRel in response to infection in humans." (PMID 27059500, 2016). "As the infection was progressing, the expression levels of REL/NF-κB, integrin β-1, peroxinectin and HSP70 were significantly up-regulated at 30 hpc, namely 2.0-, 2.0-, 5.7-, and 2.3-fold, respectively (p < 0.05, Student’s t-test)." (PMID 34361958, 2021). "The NFκB complex consists of 5 proteins [NFκB1 (p105), NFκB2 (p100), RELA (p65), RELB and REL (c-Rel)] and, upon activation, provides a powerful defense mechanism against infection and stress; regulation of the complex in managed in part by families of NFκB inhibitor genes (IκB) and kinases (IKK)." (PMID 27078000, 2016). "c-REL deficient CD8+ T cells aberrantly become anergic in vitro under conditions that would normally favor effector differentiation, although cells unable to activate c-REL differentiated normally during infection in vivo, indicating that other factors can compensate for c-REL deficiency." (PMID 33072137, 2020). "Interestingly, before infection, the expression levels of many of these master regulators (e.g., REL, NFKB1, RELB, IRF2, IRF9) were different across the three species, while post-infection, their expression converged to practically the same level, regardless of species." (PMID 21187902, 2010). "Pathways involved in chemokine receptor signaling were also significantly enriched, highlighting the recruitment of immune cells to the site of infection (NFKBIA, NFKBIB, NFKBIE, NFKBIZ, TNFAIP3, REL, BCL3)." (PMID 40634947, 2025). "The synergy between REL and GATA transcription factors is a common feature in regulating immune genes, as demonstrated in Drosophila, where serpent and REL-containing transcription factors such as Dorsal and Dif collaborate to ensure robust immune responses during infection." (PMID 39707409, 2024).
inflammation (5 papers, 2015 to 2022). Aberrant reaction of the microcirculation characterized by movement of fluid and leukocytes from the blood into extravascular tissues. "REL, however, is an essential transcription factor for lymphocyte development and plays a critical role in autoimmune inflammation." (PMID 26158728, 2015). "IRF1 and REL, a member of the NF-κB family, are key mediators of VCAM1 expression during endothelial inflammation." (PMID 35406678, 2022).
hematologic malignancies (2 papers, 2013 to 2018). "For example, NOTCH2 was reported to promote cell proliferation in T-ALL cell lines;30 the stably upregulated REL as a TF could decrease cell apoptosis of hematologic malignancies." (PMID 30195757, 2018).
hematological cancers (2 papers, 2018). "While non-canonical NF-κB RELB signaling is described to be mostly present in hematological cancers, solid cancers reveal canonical NF-κB RELA (p65) and/or c-REL activity." (PMID 29673141, 2018). "While non-canonical NF-κB RELB signaling is described to be mostly present in hematological cancers, solid cancers reveal constitutive canonical NF-κB RELA or c-REL activity." (PMID 29673141, 2018).
skin disorder (1 paper, 2021). Any deviation from the normal structure or function of the skin or subcutaneous tissue that is manifested by a characteristic set of symptoms and signs. "Polymorphisms in human IL1RN have been associated with in vivo control of Epstein–Barr viral load, and with inflammatory bowel and skin disorders that have also been associated with the REL locus." (PMID 34707143, 2021).
REL also shares sentences with these, for which no sentence is quoted: inflammatory bowel disease (7 papers); leukemia (7); pancreatic cancer (7); celiac disease (6); osteosarcoma (5); ovarian carcinoma (5); papillary thyroid cancer (5); asthma (4); multiple myeloma (4); Parkinsonism (4); ulcerative colitis (4); Anxiety (3); breast tumor (3); glioma (3); head and neck cancer (3); liver (3); systemic lupus erythematosus (3); Adult T-cell leukemia (2); allergies (2); Arthritis (2); bacterial infection (2); Cachexia (2); cancer of adrenal glands (2); choriocarcinoma (2); Cognitive impairment (2); colorectal cancer (2); Crohn disease (2); cryptosporidiosis (2); diabetes (2); gastric cancer (2).
A further 90 diseases each share a sentence with REL in 2 papers or fewer.